CHD1 (chromodomain helicase DNA binding protein 1)
Diseases named in the same sentence as CHD1 in open-access papers (continued):
Sharing a sentence is not in itself a finding about the gene and the disease.
prostate tumors (9 papers, 2014 to 2024). "In prior studies, we found that CHD1 deletions show a mutually exclusive pattern with PTEN loss in prostate tumors, and CHD1 negatively correlates with PTEN expression at protein levels." (PMID 36776288, 2023). "In contrast, CHD1 deletion is mutually exclusive with PTEN loss or TMPRSS2:ERG fusion in human prostate tumors, by crosstalk with key components in PTEN-AKT and AR signaling pathways." (PMID 36776288, 2023). "In prostate tumors, loss of CHD1 causes DNA repair defects, androgen receptor (AR) redistribution and dysfunction, chromatin instability, and transcriptional plasticity." (PMID 36776288, 2023). "Mechanistically, PTEN loss stabilizes CHD1 protein in cancer cells and prostate tumors by disrupting CHD1’s ubiquitination and degradation." (PMID 36776288, 2023). "In PTEN-deficient prostate tumors, CHD1 deletion caused reduced MDSC infiltration and increased CD8+ T cells." (PMID 36776288, 2023). "Recent cancer genomic studies identified recurrent mutations and deletions of the CHD1 gene in prostate tumors (8-10%), uterine (11%), melanoma (7%), and colorectal cancers (6%)." (PMID 36776288, 2023). "However, in PTEN-deficient prostate tumors, the CHD1 protein is stabilized and contributes to cancer progression, tumor microenvironment remodeling, and drug resistance." (PMID 36776288, 2023). "Another study in AA men revealed that, compared to cases with either alteration alone, prostate tumors with both CHD1 deletion and SPOP mutations showed significantly higher levels of HR deficiency-associated signatures and large-scale structural rearrangements." (PMID 36776288, 2023). "Preclinical studies showed that CHD1 loss-induced HR defects sensitize prostate tumors to PARP inhibitors, Olaparib and Talazoparib, both in vitro and in vivo, suggesting CHD1 might be a predictive biomarker." (PMID 36776288, 2023). "We found that subclonal deletion of CHD1 is nearly three times as frequent in prostate tumors of African American men than in men of European ancestry and it associates with rapid disease progression." (PMID 38645014, 2024). "Given the context-dependent role of CHD1 in prostate tumors, genes showing co-occurrence (SPOP or MAP3K7) or mutual exclusivity (ERG and PTEN) should also be considered as influence factors in these clinical studies." (PMID 36776288, 2023). "Using whole exome sequencing, FISH, or confocal microscopy, several groups showed the mutual exclusivity of CHD1 deletion with ERG fusion in human prostate tumors." (PMID 36776288, 2023). "As a direct target gene of CHD1, IL-6 mediates the recruitment and activation of MDSCs in prostate tumors." (PMID 36776288, 2023). "Phenocopying CHD1 loss, SPOP mutations also cause genomic instability and impaired HR DSB repair, as well as promote the sensitivity of prostate tumors to DNA-damaging therapeutic agents, such as PARP inhibitors." (PMID 36776288, 2023). "Another recent study uncovered that subclonal deletion of CHD1 is about three times more frequent in prostate tumors of African American (AA) men (29.7%) than that of European Ancestry (EA) men (11%)." (PMID 36776288, 2023). "In both models, we found that CHD1 depletion significantly delayed the development and progression of PTEN-deficient prostate tumors and prolonged the survival of mice, providing genetic evidence supporting the essential roles of CHD1 in the context of PTEN defects." (PMID 36776288, 2023). "For example, CHD1 deletions and SPOP mutations frequently co-occur in prostate tumors." (PMID 36937425, 2023). "Our recent studies in GEM and syngeneic models revealed that depletion of CHD1 reverses the immunosuppressive TME and sensitizes prostate tumors to the checkpoint immunotherapy." (PMID 36776288, 2023). "Besides, we identified IL-6 as a direct target of CHD1 and mediates the recruitment and activation of MDSC, which contributes to T cell suppression in the prostate tumors." (PMID 36776288, 2023).
prostate tumors (continued). "Loss of the CHD1 and MAP3K7 genes can also promote the development of prostate tumors in the absence of SPOP mutations." (PMID 26506153, 2015). "Interestingly, prostate tumors with evidence of the tandem duplication genotype were all ETS and CHD1 wild type, hinting at a distinct and novel molecular subtype." (PMID 25155515, 2014). "Likewise, in prostate tumour cells, direct methylation of KDM1A by the protein-methyltransferase EHMT2 facilitates an interaction between the chromatin remodeling proteins CHD-1 and KDM1A, that is necessary for androgen receptor dependent transcriptional activation." (PMID 33068438, 2020). "In addition to confirming the presence of recurrent CaP genomic alterations such as TMPRSS2-ERG fusion, PTEN and CHD1 deletions, a novel recurrent deletion of LSAMP gene on chromosome 3q13.31 was found to more prevalent in prostate tumors from AA men compared to CA men (26% vs. 7%)." (PMID 29690565, 2018). "Furthermore, it is of note that the five prostate tumors putatively identified with the tandem duplication genotype were ETS rearrangement negative, CHD1 wild-type, and where genotyping was carried out, SPOP wild-type (tumor T4 was also CHD1 and SPOP wild-type)." (PMID 25155515, 2014).
gastric cancer (6 papers, 2016 to 2025). A primary or metastatic malignant neoplasm involving the stomach. "The elevated risk with a FDR affected by first primary stomach cancer may be related to a type of hereditary diffuse gastric cancer associated with germline mutation of CHD1." (PMID 34772394, 2021). "Though not previously implicated in GBC, CHD1 is a known gastric cancer driver and PIK3R2 is frequently mutated in endometrial cancers." (PMID 32839463, 2020).
colorectal cancer (4 papers, 2012 to 2023). A primary or metastatic malignant neoplasm that affects the colon or rectum. "In KRAS-mutated colorectal cancer, CHD1 protein is hyper-SUMOylated by the SUMO E2 ligase UBC9, and depletion of CHD1 impairs the KRAS-driven transformation." (PMID 36776288, 2023). "CHD1 colorectal carcinoma cells are positive for Abi1, hnRNP K and Laminin5γ2 in Western immunoblotting." (PMID 24913355, 2014).
epilepsy (4 papers, 2018 to 2023). A brain disorder characterized by episodes of abnormally increased neuronal discharge resulting in transient episodes of sensory or motor neurological dysfunction, or psychic dysfunction. "The patients with mutations in CHD1/3/7/8 genes had epilepsy as a concomitant symptom of developmental abnormalities, while CHD2 mutations caused epileptic encephalopathy as a core phenotype." (PMID 34109749, 2021). "All CHD family genes were associated with neurodevelopmental disorders, while CHD1/2/3/7/8 genes were also implicated in epilepsies or seizures." (PMID 34109749, 2021). "Additionally, there are also variants in genes related to epilepsy, such as CACNA1D (AUT142), CHD1 (AUT183), KMT2E (AUT184), and CHD2 (AUT195)." (PMID 38003033, 2023). "CHD proteins play an important role in neurodevelopment, as pathogenic variants in CHD1, CHD2, CHD4, CHD7 and CHD8 have been associated with a range of neurological phenotypes, including autism spectrum disorder (ASD), intellectual disability (ID) and epilepsy." (PMID 29962935, 2018).
developmental delay (3 papers, 2015 to 2021). "In contrast to patients with CHARGE syndrome, in whom developmental delay and learning disabilities are rare, the majority of patients with CHD1/2/4/8 pathogenic variants present with intellectual disability (ID) or developmental delay." (PMID 29962935, 2018).
lung carcinoma (2 papers, 2021 to 2022). "The results indicated that the remaining genes, apart from CHD1 and CHD8, were strongly linked to preimmune stages in lung cancer." (PMID 35467222, 2022). "Perturbation of CHD1/6 might remodel the tumor immune microenvironment and suggest that targeting CHD family members can be combined with immunotherapies in lung cancer in the future." (PMID 35467222, 2022).
melanoma (2 papers, 2012 to 2026). A malignant, usually aggressive tumor composed of atypical, neoplastic melanocytes. "Immune checkpoint blockade is more effective in a syngeneic mouse model of melanoma deficient in Chd1 and Map3k7 and is associated with elevated intra-tumoral CD8+ T cell numbers and activation." (PMID 41564866, 2026).
pancreatic cancer (2 papers, 2011 to 2019). "Western blot analysis along with corresponding quantification data provided below the immunoblotting figures shows that knockdown of hPaf1/PD2 in pancreatic cancer cells leads to a decrease in the level of CHD1 compared to the scrambled control cells." (PMID 22046413, 2011). "Western blot analysis of the co-immunoprecipitates shows that PD2 interacts with CHD1 in both cytoplasm as well as nuclear extracts of pancreatic cancer cells, Panc1 and MiaPaCa." (PMID 22046413, 2011). "PD2 and CHD1 were also observed to have a similar distribution pattern in cytoplasm and nuclear extract of other pancreatic cancer cells." (PMID 22046413, 2011). "hPaf1/PD2 was also found to interact and colocalize with CHD1 in both cytoplasmic and nuclear extracts of pancreatic cancer cells." (PMID 22046413, 2011). "Our results also show that PD2 interacts with CHD1 both in cytoplasm as well as in the nucleus of pancreatic cancer cells." (PMID 22046413, 2011). "Given that hPaf1/PD2 regulated histone methylation at the H3K4 residue, we investigated CHD1 regulation by hPaf1 by transient knockdown of hPaf1/PD2 in pancreatic cancer cells and analyzed the variation in levels of the CHD1 protein." (PMID 22046413, 2011). "Concurrently, overexpression of PD2 in HPAF/CD18 pancreatic cancer cells also upregulates CHD1 expression." (PMID 22046413, 2011). "Overall, our results suggest that hPaf1/PD2 in association with MLL1 regulates methylation of H3K4 residues, as well as interacts and regulates nuclear shuttling of chromatin remodeling protein CHD1, facilitating its function in pancreatic cancer cells." (PMID 22046413, 2011). "In pancreatic cancer, the hPaf1 subunit of the human RNA polymerase II-associated factor (PAF) complex is overexpressed, and it interacts with and regulates the expression of CHD1 and the nuclear import of CHD1, facilitating the nucleosomal remodeling in pancreatic cancer cells." (PMID 31769422, 2019). "Therefore, decreased nuclear accumulation of CHD1 in PD2 knockdown cells indicates that hPaf1/PD2 facilitates the nuclear import of CHD1 in pancreatic cancer cells to carry out its function." (PMID 22046413, 2011). "Future studies may address the genes whose expression is controlled by such an interaction between hPaf1 and CHD1 and its significance in pancreatic cancer development and progression." (PMID 22046413, 2011). "Interestingly, PD2 knockdown pancreatic cancer cells seemed to have reduced nuclear localization of CHD1 compared to the scrambled cells, suggesting that the process of CHD1 nuclear shuttling is hampered due to hPaf1 knockdown." (PMID 22046413, 2011). "Therefore, our results suggest that the hPaf1/PD2 subunit of the human PAF complex interacts with the chromatin remodeling protein CHD1 in pancreatic cancer cells, facilitating its nuclear import and thereby regulating its function of nucleosomal remodeling." (PMID 22046413, 2011). "A single study in pancreatic cancer cells suggested that CHD1 might have a pro-oncogenic function." (PMID 31769422, 2019). "To this end, we compared the CHD1 distribution in the cytoplasm and nucleus of pancreatic cancer cells between scrambled and PD2 knockdown pancreatic cancer cells using confocal microscopy." (PMID 22046413, 2011). "The CHD1 staining (red) was found to overlap with the PD2 staining (green), both in cytoplasm as well as in the nucleus of pancreatic cancer cells in corroboration with the biochemical data." (PMID 22046413, 2011). "Furthermore, hPaf1/PD2 knocked down pancreatic cancer cells show an altered pattern of micrococcal nuclease digestion compared to the control cells, indicating that PD2 might play an important role in chromatin structure rearrangement through CHD1 in pancreatic cancer." (PMID 22046413, 2011).
pancreatic cancer (continued). "Given that hPaf1/PD2 interacts as well as regulates the level of CHD1 in pancreatic cancer cells, and their similarity in pattern of nuclear-cytoplasmic localization, we tested whether PD2 helps in nuclear transport of CHD1 in pancreatic cancer cells." (PMID 22046413, 2011).
B-cell lymphoma (1 paper, 2017). "In naïve cells, genes up-regulated with age were most enriched for ChIP-seq peaks from the CHD1 transcription factor, although this dataset was from experiments performed in the CH12 (mouse B-cell lymphoma) cell line." (PMID 28642803, 2017).
cleft palate (1 paper, 2022). Cleft palate is a fissure type embryopathy that affects the soft and hard palate to varying degrees. "In addition, missense and copy number variants of CHD1 contributed to craniofacial malformations, including cleft palate in human patients." (PMID 36291147, 2022).
clubfoot (1 paper, 2024). The most common congenital deformation of the foot, occurring in 1 of 1,000 live births. "Initially, genes associatedwith clubfoot (PITX1, TBX4, HOXA9, HOXD10, HOXD12,HOXD13, HOXA9, TPM1, TPM2, COL9A1, FLNB, CASP8,CASP10, UTX, CHD1, RIPPLY2, CAND2, WNT7) werescreened for potential variants." (PMID 38952703, 2024).
colon adenocarcinoma (1 paper, 2019). "For example, methylation of APC1A, CHD1, DKK3, and MYOD is associated with prognosis in colon adenocarcinoma patients." (PMID 31852837, 2019).
colorectal adenocarcinoma (1 paper, 2023). The most common type of colorectal carcinoma. "Thus, lncRNA LINC02535 was confirmed to induce colorectal adenocarcinoma progression via targeting miR-30d-5p/CHD1 axis, and circ-SFMBT2 sponges miR-30d-5p that directly targets CHD1 and therefore plays an oncogenic role in colorectal adenocarcinoma." (PMID 37175555, 2023).
colorectal tumors (1 paper, 2024). "Nonetheless, we observed some nominally significant differential associations in 12 genes, including positive associations between folate intake and the risk of CHD1-, DOCK3-, and ZNF521-mutated colorectal tumors, which warrant replication in future studies." (PMID 39025327, 2024). "It is known that CHD1 is particularly expressed in microsatellite instability (MSI)-high colorectal tumors." (PMID 39025327, 2024).
diffuse large B-cell lymphoma (1 paper, 2019). "Similar to CHD1, PDS5B deletion was detected in 50% of the cancer types; the highest deletion frequencies were in PCA, sarcoma and diffuse large B-cell lymphoma." (PMID 31222142, 2019).
emphysema (1 paper, 2014). "Other biomarkers such as CHD1, CDH13 and SERPINA7 may also have a role in evaluating emphysema (especially milder emphysema), although require confirmation in other cohorts." (PMID 25306249, 2014).
endometrial cancer (1 paper, 2014). Primary or metastatic malignant neoplasm involving the endometrium (mucous membrane that lines the endometrial cavity). "The role of CHD1 in endometrial cancer remains to be determined." (PMID 25286960, 2014).
HIV-1 infection (1 paper, 2014). The type species of lentivirus and the etiologic agent of acquired immunodeficiency syndrome (AIDS). "Thirdly, siRNAs targeting CHD1 reduced HIV-1 infection of human SupT1 T cells." (PMID 25297984, 2014). "Future studies will provide a more detailed view of the role of CHD1 and CHD2 in the transcription cycle of HIV-1 infection and will further contribute to our understanding of epigenetic regulation of transcription during HIV infection." (PMID 25297984, 2014). "Gain-of-function and loss-of-function experiments performed in human cells confirmed that CHD2 and the highly related CHD1 protein positively regulate MLV and HIV-1 infection." (PMID 25297984, 2014). "Secondly, gain-of-function and loss-of-function experiments in HEK293T cells confirmed that CHD2 and the highly related CHD1 protein positively regulate MLV and HIV-1 infection." (PMID 25297984, 2014). "The siRNAs targeting both CHD-1 and CHD-2 also led to a modest but highly reproducible and statistically significant decrease in HIV-1 reporter gene expression in human SupT1 cells, a T-cell line that is more physiologically relevant for HIV-1 infection." (PMID 25297984, 2014).
liver cancer (1 paper, 2020). An epithelial or non-epithelial malignant neoplasm that arises from the liver.
lobular carcinomas (1 paper, 2021). "The higher frequency of CDH1 loss-of-function mutations and the lower transcriptional expression of the CHD1 gene in lobular carcinomas were some of the main differences between the two histotypes." (PMID 33808143, 2021).
lung adenocarcinoma (1 paper, 2022). A carcinoma that arises from the lung and is characterized by the presence of malignant glandular epithelial cells. "Similar paradoxical phenomena also existed in lung squamous cell carcinoma, in which CHD1/2 was downregulated and its high expression was associated with poor OS and FP, and in lung adenocarcinoma, in which CHD3 was downregulated, its high expression was linked to poor OS and FP." (PMID 35467222, 2022). "In addition, the results from our study demonstrated that the mRNA expression of CHD4/6/7/8 was remarkably linked with cancer stage in patients with lung adenocarcinoma, and CHD1/2/4/6/7/9 was associated with cancer stage in patients with lung squamous cell carcinoma." (PMID 35467222, 2022). "For example, in lung adenocarcinoma, CHD1/4/6/7/8 was significantly overexpressed, whereas CHD3 was downregulated." (PMID 35467222, 2022).
lung squamous cell carcinoma (1 paper, 2022). "Compared with normal lung tissues, the expression of CHD4/6/7/8 in lung squamous cell carcinoma was higher, while the expression of CHD1/2, and to a less extent, was lower." (PMID 35467222, 2022).
lymphoid cancer (1 paper, 2023). "Mutations in two novel genes, CHD1 and DDX11, demonstrated a negative impact on survival in AML/MDS and lymphoid cancer data from the Cancer Genome Atlas (TCGA)." (PMID 37041565, 2023).
meningioma (1 paper, 2021). A generally slow growing tumor attached to the dura mater. "Importantly, endogenous Merlin co-immunoprecipitated with the PAFC components as well as CHD1 and VPRBP in IOMM-Lee meningioma cells, confirming that these interactions take place at physiological levels of Merlin as well as in the absence of SV40 Large T antigen that is expressed in HEK293T cells." (PMID 34424918, 2021).
mesothelioma (1 paper, 2021). A usually malignant and aggressive neoplasm of the mesothelium which is often associated with exposure to asbestos. "For non-mesothelioma cell lines there was a slight negative correlation between CHD1 mRNA that was statistically, but not clinically, significant (Spearman’s rho value is −0.5257, p-value is 0.0009923, and slope of the linear regression model is −0.0008789 which is close to zero)." (PMID 34638565, 2021).
metastatic prostate carcinoma (1 paper, 2019). A carcinoma that arises from the prostate gland and has spread to other anatomic sites.